RNU6-574P (RNA, U6 small nuclear 574, pseudogene)
Gene: Small nuclear RNA gene on chromosome 12 (51,987,657 to 51,987,763, forward strand). Ensembl gene ENSG00000206992.
Homologues: Orthologues: chimpanzee U6 (98% identical), macaque U6 (96% identical), rat U6 (92% identical). Paralogues in human: RNU6-38P (95% identical), RNU6-25P (94% identical), RNU6-1 (93% identical), RNU6-1158P (93% identical), RNU6-15P (93% identical), RNU6-166P (93% identical), RNU6-2 (93% identical), RNU6-20P (93% identical), RNU6-3P (93% identical), RNU6-4P (93% identical), RNU6-5P (93% identical), RNU6-6P (93% identical), and 1289 more.